MRPL37 (mitochondrial ribosomal protein L37)
Synonyms: L2mt; MRP-L2; L37mt; MRP-L37; MRPL2; RPML2; mL37
Tractability: Small molecule: a structure with a bound ligand is known. PROTAC: ubiquitination databases record sites on it; its protein half-life has been measured.
Target class: Other cytosolic protein
Safety:
Unwanted effects reported when the protein is acted on. In parentheses: how it was acted on, where the effect was seen, and who reports it.
neutropenia (source: ClinPGx)
Gene: Protein-coding gene on chromosome 1 (54,184,041 to 54,225,464, forward strand). Ensembl gene ENSG00000116221.
Subcellular location: Mitochondrion
Subcellular location (Human Protein Atlas): Mitochondria
Pathways (Reactome):
Metabolism of proteins: Mitochondrial ribosome-associated quality control; Mitochondrial translation elongation; Mitochondrial translation initiation; Mitochondrial translation termination
Gene Ontology:
Molecular function: RNA binding; structural constituent of ribosome
Biological process: mitochondrial translation; translation
Cellular component: mitochondrial large ribosomal subunit; mitochondrion; mitochondrial inner membrane; mitochondrial ribosome; ribosome
Genetic constraint (gnomAD): Loss-of-function variants: 34 observed, 46.76 expected, observed/expected ratio (o/e) 0.73, 90% interval 0.55 to 0.97. The upper end of that interval is the gene's LOEUF score, 0.97, which puts it in group 4 of 6, group 1 being the genes least tolerant of losing a copy. Missense variants: 532 observed, 574.77 expected, observed/expected ratio (o/e) 0.93, 90% interval 0.86 to 0.99. Synonymous variants: 212 observed, 234.26 expected, observed/expected ratio (o/e) 0.9, 90% interval 0.81 to 1.01.
Homologues: Orthologues: chimpanzee MRPL37 (95% identical), macaque MRPL37 (90% identical), pig MRPL37 (85% identical), rabbit MRPL37 (84% identical), guinea pig MRPL37 (80% identical), dog MRPL37 (80% identical), mouse Mrpl37 (80% identical), rat Mrpl37 (79% identical), tropical clawed frog mrpl37 (49% identical), zebrafish mrpl37 (48% identical), Drosophila melanogaster mRpL37 (22% identical), Caenorhabditis elegans mrpl-37 (20% identical).
Diseases named in the same sentence as MRPL37 in open-access papers:
MRPL37 is named in the same sentence as 12 diseases in open-access papers, as found by Europe PMC text mining. Sharing a sentence is not in itself a finding about the gene and the disease. The quoted sentences say what the papers report.
lymphoma (3 papers, 2018 to 2022). A malignant (clonal) proliferation of B- lymphocytes or T- lymphocytes which involves the lymph nodes, bone marrow and/or extranodal sites. "The levels of MRPL37 and mRNA were also significantly elevated in different lymphoma tissues." (PMID 36233293, 2022). "MRPL37 mRNA expression is increased in lymphoma human tissues and cells." (PMID 29531015, 2018). "MRPL37 is highly expressed in lymphoma tissues and cells, and may be related to cell apoptosis." (PMID 33758616, 2021).
colorectal cancer (2 papers, 2024 to 2025). A primary or metastatic malignant neoplasm that affects the colon or rectum. "One study found that MRPL37 is associated with metastasis inhibition in colorectal cancer, with interactions between MRPL37 and SLC25A10 through MRPL1 reinforcing its synergistic role." (PMID 41399509, 2025). "Contrarily, MRPL37 was associated with metastasis inhibition in colorectal cancer, with interactions with SLC25A10 through MRPL1 also identified." (PMID 39354291, 2024). "However, in colorectal cancer, MRPL37 is downregulated, and its lower expression is associated with increased metastasis." (PMID 41399509, 2025). "In LUAD, MRPL37 appears to contribute to more aggressive tumour subtypes, while it has been indicated as part of a metastasis inhibition network in colorectal cancer." (PMID 39354291, 2024).
cholangiocarcinoma (1 paper, 2025). A carcinoma that arises from the intrahepatic biliary tree (intrahepatic cholangiocarcinoma) or from the junction, or adjacent to the junction, of the right and left hepatic ducts (hilar cholangiocarcinoma). "Additionally, given that the in vivo spontaneous tumor model used in this study, AKT/NRAS, induces combined hepatocellular-cholangiocarcinoma, further investigation is required to assess the role of MRPL37 in cholangiocarcinoma cells." (PMID 41399509, 2025).
colon cancer (1 paper, 2021). "Finally, the GTPase ERAL1, mitochondrial ribosomal proteins ERAL1, MRPL11, MRPL15, MRPL30, MRPL37, MRPL40, and MRPL52 were determined to be hub proteins with a commonly down-regulated trend in four berberine-treated colon cancer cell lines." (PMID 33806918, 2021).
COVID-19 (1 paper, 2023). A disease caused by infection with severe acute respiratory syndrome coronavirus 2. "For example, MRPL37 showed an increased observation frequency from 216 tryptic peptides from SEQUEST in the NHP samples to 760 observations in COVID-19 that is an increase of more than threefold with a χ2 value of χ2 = 1364 where χ2 = 9 is the cut off for significance." (PMID 37031181, 2023). "A comparison of the proteins in COVID versus ICU-ARDS and normal controls from tryptic or optional phospho/tryptic peptides showed that CYTB, ND5, MRPL37 and ALDH2 were the most specifically elevated mitochondrial proteins in COVID-19 plasma." (PMID 37031181, 2023). "Mitochondrial proteins such as ATP5A1, CYB561D1, several CYP accessions, L2HGDH, two MRP, MRPL37, NDUFS1 and others showed increased observation frequency across COVID-19 and ICU-ARDS versus NHP individually by the Chi Square test (χ2 ≥ 10, p ≤ 0.01) and as a group by one way ANOVA (p ≤ 0.003)." (PMID 37031181, 2023).
liver cancer (1 paper, 2025). An epithelial or non-epithelial malignant neoplasm that arises from the liver. "Both univariate and multivariate Cox regression analyses confirmed that MRPL37 has the highest hazard ratio, further establishing it as a critical independent molecular marker for diagnosis and prognosis in liver cancer." (PMID 41399509, 2025). "Collectively, these findings suggest that MRPL37 plays an essential role as an oncogenic driver in liver cancer tumorigenicity both in vitro and in vivo." (PMID 41399509, 2025). "In this study, we constructed a subtype classification and prognostic model for liver cancer based on the MRPL gene family, identifying MRPL37 as a key gene associated with HCC progression." (PMID 41399509, 2025). "While our study provides strong evidence for the role of MRPL37 in liver cancer, several limitations must be acknowledged." (PMID 41399509, 2025). "The results showed that MRPL37 had the highest hazard ratio, and its mRNA level was also significantly upregulated in liver cancer tissues." (PMID 41399509, 2025). "The functional role of MRPL37 in promoting liver cancer progression was further validated through both in vitro and in vivo models." (PMID 41399509, 2025). "Our study demonstrates that MRPL37 plays a pivotal role in the metabolic shift of liver cancer cells by regulating mitochondrial protein synthesis and OXPHOS." (PMID 41399509, 2025). "By influencing key mitochondrial processes, MRPL37 promotes liver cancer progression and contributes to poor prognosis." (PMID 41399509, 2025). "We further investigated the functional role of MRPL37 in liver cancer progression through in vitro and in vivo models, demonstrating its regulatory impact on mitochondrial metabolism and tumorigenesis." (PMID 41399509, 2025). "In the spontaneous liver cancer model, MRPL37 knockdown significantly impaired liver tumor formation, as evidenced by fewer and smaller tumors compared to the control group." (PMID 41399509, 2025). "Here, we leveraged The Cancer Genome Atlas (TCGA) liver cancer data to develop a subtype classification and prognostic model based on the MRPL family genes, identifying MRPL37 as a key gene associated with HCC progression." (PMID 41399509, 2025). "In vivo, silencing MRPL37 reduces tumor growth in both xenograft and spontaneous liver cancer models." (PMID 41399509, 2025). "Second, although we have highlighted the clinical relevance of MRPL37 in liver cancer prognosis, additional validation in larger, independent patient cohorts is needed to confirm its potential as a reliable prognostic biomarker." (PMID 41399509, 2025). "Our findings suggest that MRPL37 could serve as a potential therapeutic target for liver cancer, offering a foundation for the development of treatment strategies aimed at disrupting mitochondrial function and reprogramming tumor metabolism." (PMID 41399509, 2025). "Furthermore, MRPL37 knockdown in xenograft and spontaneous liver cancer models significantly inhibited tumor growth, highlighting its essential role in liver cancer tumorigenesis." (PMID 41399509, 2025). "Our findings suggest that MRPL37 could serve as a therapeutic target in liver cancer." (PMID 41399509, 2025). "Through the combination of in vitro and in vivo experiments, along with RNA-seq, proteomics, and targeted metabolomics, we uncovered that MRPL37 may regulate mitochondrial energy metabolism and mitochondrial function, thereby influencing the malignant progression of liver cancer." (PMID 41399509, 2025). "Our results suggest MRPL37 as a critical regulator of energy metabolism in HCC, highlighting its potential as a therapeutic target for liver cancer." (PMID 41399509, 2025). "In our study, we found that MRPL37 is highly expressed in HCC across multiple tumor databases, and its high expression correlates with poor prognosis in liver cancer patients." (PMID 41399509, 2025).
liver cancer (continued). "Additionally, single-cell RNA-seq data from liver cancer tissues (GSE149614 and GSE166635) showed that MRPL37 was highly expressed in cancer cells compared to other cell types." (PMID 41399509, 2025).
lung adenocarcinoma (1 paper, 2025). A carcinoma that arises from the lung and is characterized by the presence of malignant glandular epithelial cells. "In lung adenocarcinoma, high expression of MRPL37 correlates with poor prognosis." (PMID 41399509, 2025).
cancer (2 papers, 2025). A tumor composed of atypical neoplastic, often pleomorphic cells that invade other tissues. "To date, there are limited reports on MRPL9 and MRPL37 in cancer, and our understanding of their roles in the disease is still limited." (PMID 39859078, 2025). "The role of MRPL37 in tumor progression has been well-documented across various cancer types, though its function varies between tumors." (PMID 41399509, 2025). "MRPL37 is dysregulated in some types of cancer, including ESCA, CRC, and breast cancer." (PMID 39859078, 2025). "MRPS17 and several gene signatures containing MRPs such as MRPL37, MRPS34, and MRPL11 may be independent indicators for cancer patients treated with chemotherapy or chemoradiotherapy." (PMID 39859078, 2025).
tumor (2 papers, 2024 to 2025). "Further, tumor stemness analysis showed that the mRNAsi score was significantly higher in the MRPL37 high-expression group, suggesting its association with enhanced tumor stemness and resistance to chemotherapy and radiotherapy." (PMID 41399509, 2025). "Additionally, upregulation of MRPL37 in HCC has been associated with increased tumor stemness, immune evasion, and resistance to immune therapy." (PMID 41399509, 2025). "The differential roles of MRPL37 across various tumors likely reflect differences in tumor stages, metabolic demands, and the tumor microenvironment." (PMID 41399509, 2025). "The results showed that MRPL37 silencing significantly inhibited tumor growth, with marked reductions in both tumor volume and weight, compared to the control group." (PMID 41399509, 2025). "Histological analysis through hematoxylin and eosin staining revealed reduced the tumor burden in the MRPL37 knockdown group." (PMID 41399509, 2025). "In summary, our study provides strong evidence that MRPL37 plays a pivotal role in regulating mitochondrial function, energy metabolism, and tumor progression in HCC." (PMID 41399509, 2025). "IHC analysis further demonstrated significantly lower expression levels of tumor biomarkers CK-19 and Ki67 in liver samples from the MRPL37 knockdown group." (PMID 41399509, 2025). "Our findings indicate that high MRPL37 expression is significantly associated with the upregulation of immune evasion genes such as PD-L1 and TIM-3, which are known to contribute to immune suppression in the tumor microenvironment." (PMID 41399509, 2025). "Existing studies have suggested that MRPL37 and MRPL28 may be involved in cell transformation, proliferation, and apoptosis of tumor cells." (PMID 38886335, 2024). "Similarly, western blot (WB) analysis of fresh tumor tissues from 28 HCC patients confirmed the upregulation of MRPL37 expression in tumor tissues compared to adjacent non-cancerous tissues." (PMID 41399509, 2025).
MRPL37 also shares sentences with these, for which no sentence is quoted: breast carcinoma (2 papers); hepatocellular carcinoma (1); infection (1).